ADAMTS2 (ADAM metallopeptidase with thrombospondin type 1 motif 2)
Description:
Cleaves the propeptides of type I and II collagen prior to fibril assembly (By similarity). Does not act on type III collagen (By similarity). Cleaves lysyl oxidase LOX at a site downstream of its propeptide cleavage site to produce a short LOX form with reduced collagen-binding activity.
Synonyms: ADAM-TS2; ADAMTS-2; PC I-NP; pNPI; PCINP; PCPNI; ADAMTS-3; hPCPNI; NPI; EDSDERMS; PCI-NP
Tractability: Antibody: its Gene Ontology location is reachable by antibodies, with high confidence; UniProt places it where antibodies can reach, with medium confidence; UniProt predicts a signal peptide or a membrane-spanning region; the Human Protein Atlas places it where antibodies can reach.
Gene: Protein-coding gene on chromosome 5 (179,110,853 to 179,345,461, reverse strand). Ensembl gene ENSG00000087116.
Subcellular location: Secreted, extracellular space, extracellular matrix
Subcellular location (Human Protein Atlas): Plasma membrane; Vesicles; Predicted to be secreted
Pathways (Reactome):
Disease: Defective B3GALTL causes PpS
Extracellular matrix organization: Collagen biosynthesis and modifying enzymes
Metabolism of proteins: O-glycosylation of TSR domain-containing proteins
Gene Ontology:
Molecular function: metalloendopeptidase activity; metallopeptidase activity; peptidase activity; zinc ion binding
Biological process: collagen fibril organization; extracellular matrix organization; proteolysis
Cellular component: extracellular matrix; extracellular region
Genetic constraint (gnomAD): Loss-of-function variants: 52 observed, 115.41 expected, observed/expected ratio (o/e) 0.45, 90% interval 0.36 to 0.57. The upper end of that interval is the gene's LOEUF score, 0.57, which puts it in group 2 of 6, group 1 being the genes least tolerant of losing a copy. Missense variants: 1,483 observed, 1,648.2 expected, observed/expected ratio (o/e) 0.9, 90% interval 0.86 to 0.94. Synonymous variants: 670 observed, 668.6 expected, observed/expected ratio (o/e) 1, 90% interval 0.94 to 1.07.
Homologues: Orthologues: macaque ADAMTS2 (94% identical), pig ADAMTS2 (91% identical), rat Adamts2 (89% identical), mouse Adamts2 (89% identical), rabbit ADAMTS2 (88% identical), dog ADAMTS2 (87% identical), guinea pig ADAMTS2 (87% identical), chimpanzee ADAMTS2 (83% identical), tropical clawed frog adamts2 (63% identical), zebrafish adamts2a (56% identical), zebrafish adamts2b (6% identical). Paralogues in human: ADAMTS3 (55% identical), ADAMTS14 (51% identical), ADAMTS18 (29% identical), ADAMTS16 (29% identical), ADAMTS7 (29% identical), ADAMTS9 (28% identical), ADAMTS12 (26% identical), ADAMTS20 (26% identical), ADAMTS6 (26% identical), ADAMTS10 (26% identical), ADAMTS17 (25% identical), ADAMTS15 (25% identical), and 13 more.
Diseases named in the same sentence as ADAMTS2 in open-access papers:
ADAMTS2 is named in the same sentence as 93 diseases in open-access papers, as found by Europe PMC text mining. Sharing a sentence is not in itself a finding about the gene and the disease. The quoted sentences say what the papers report.
dermatosparaxis (12 papers, 2016 to 2025). "As mentioned, loss of the procollagen N-proteinase activity of ADAMTS2 in animals results in a disorder called dermatosparaxis." (PMID 40837410, 2025). "Variants in the ADAMTS2 gene are known to cause dermatosparaxis in humans as well as in cattle, sheep, and dogs." (PMID 37462293, 2023). "For instance, sheep with dermatosparaxis caused by a homozygous nullifying ADAMTS2 nonsense mutation, typically die or require humane euthanasia in first weeks of life." (PMID 36421833, 2022). "In cases of EDS dermatosparaxis type and arthrochalasia type, mutations in ADAMTS2 or the N-terminus of pro-α1(I)/pro-α2(I), respectively, directly impact N-propeptide cleavage regardless of cellular location or tissue environment." (PMID 33944912, 2021). "Other types include kyphoscoliotic EDS (kEDS), which causes severe muscle weakness due to PLOD1 mutations, arthrochalasia EDS (aEDS) with extreme joint laxity resulting from COL1A1 or COL1A2 mutations, and dermatosparaxis EDS (dEDS) with fragile skin due to ADAMTS2 mutations." (PMID 40542421, 2025). "Decreased N-propeptide cleavage of the type I procollagen N-propeptide can also be caused by defects in the type I procollagen N-proteinase, ADAMTS2, due to biallelic loss-of-function variants in the ADAMTS2 gene, which gives rise to the dermatosparaxis EDS type (dEDS)." (PMID 35205310, 2022). "Thus, the genomes of all 8 dogs harbored likely-causal ADAMTS2 alleles in the homozygous state, consistent with reports that dermatosparaxis is a recessive trait in other species." (PMID 36421833, 2022). "Because a high proportion of the procollagen-aminopeptidase activity expressed in the dermis of post-natal mammals is encoded by ADAMTS2, a high proportion of dermal fibrils in individuals with dermatosparaxis due to homozygous nullifying ADAMTS2 mutations have retained aminopropeptides." (PMID 36421833, 2022). "Instead, absence of ADAMTS2 activity causes dermatosparaxis EDS presenting with extreme skin fragility, characteristic craniofacial features, redundant skin with excessive skin folds at the wrists and ankles, umbilical hernia and severe bruising with a risk of subcutaneous hematomas and hemorrhages." (PMID 33816558, 2021). "Subsequently, dermatosparaxis Ehlers–Danlos syndrome (dEDS) was identified as the equivalent in humans, characterized by the presence of different mutations in the ADAMTS2 gene." (PMID 31877874, 2019). "Here, we expand the knowledge about the canine dermatosparaxis subtype of EDS by reporting two novel, likely-causal ADAMTS2 variants and describing the disease phenotypes for seven dogs carrying these variants in the homozygous state." (PMID 36421833, 2022). "ADAMTS2 was first described in dermatosparaxis, a cattle disease characterized by extreme skin fragility." (PMID 31877874, 2019). "Specifically ADAMTS2 mutations are associated with Type VIIC, which is characterized by dermatosparaxis." (PMID 26879370, 2016). "No plausibly causal ADAMTS2 variants were found in the other 22 whole genome sequences, suggesting that dermatosparaxis is a significant though uncommon subtype of canine EDS." (PMID 36421833, 2022). "The transparency of corneas from individuals with the dermatosparaxis and the minimal changes to corneal fibril ultrastructure in the affected Alapaha Blue Blood Bulldogs suggest that ADAMTS2 has a relatively minor role in collagen fibrillogenesis in the cornea." (PMID 36421833, 2022). "Animal dermatosparaxis and human dEDS are caused by biallelic mutations in ADAMTS2, encoding a disintegrin and metalloproteinase with thrombospondin-motifs Type 1 Motif-2 (ADAMTS-2)." (PMID 34712265, 2021). "In order to clarify why arthrochalasia and dermatosparaxis EDS display different clinical phenotypes and to investigate the diverse functions of ADAMTS2 and ADAMTS14 in vivo, N-Tails analysis has been performed on skin samples from wild-type mice (Wt) and TS2−/−, TS14−/− and TS2−/−TS14−/−." (PMID 33816558, 2021).
dermatosparaxis (continued). "Although the cutaneous features of Adamts2–/– mice largely mimic findings in human dEDS skin, age-dependent changes have not been reported in dEDS patients or animal dermatosparaxis." (PMID 34712265, 2021).
cardiac hypertrophy (10 papers, 2018 to 2025). "ADAMTS2 was also mentioned as a cardioprotective factor in a study where ADAMTS16 was identified as a promotor of cardiac hypertrophy." (PMID 40837410, 2025). "Together, these observations suggest an essential protective role for ADAMTS2 in the progression of heart failure and cardiac hypertrophy and identify ADAMTS2 and its signaling pathways as potential therapeutic targets." (PMID 40837410, 2025). "A limited number of studies have suggested a role for ADAMTS2 in cardiovascular disease, including pediatric stroke, cerebral aneurysm formation, acute myocardial infarction, heart failure, and cardiac hypertrophy." (PMID 40837410, 2025). "This phenotype of cardiac hypertrophy, fibrosis, and dysfunction was blunted in transgenic mice with cardiac-specific overexpression of ADAMTS2." (PMID 40837410, 2025). "Another in vivo pressure overload mouse model showed that ADAMTS2 was upregulated during cardiac hypertrophy." (PMID 35224040, 2022). "Associations have been detected between genetic variants within ADAMTS2 and body fat distribution to the trunk, and downregulated ADAMTS2 expression in heart tissues has been described in cardiac hypertrophy induced by pressure overload." (PMID 36182916, 2022). "We also detected the DEG ADAMTS2, which was previously found to participate in cardiac hypertrophy." (PMID 37450589, 2023). "ADAMTS2 is mainly secreted from fibroblasts and plays important roles in fibrosis, with elevated expression levels observed in fibrotic lesions and diseases such as cardiac hypertrophy, osteoarthritis, and squamous cell carcinoma." (PMID 37623492, 2023). "In the pressure overload mouse model, ADAMTS2 was upregulated during cardiac hypertrophy." (PMID 35224040, 2022). "ADAMTS2 may serve as a promising target for preventing cardiac hypertrophy and heart failure." (PMID 37239897, 2023). "A total of six hub genes (TANC2, ADAMTS2, DYNLL1, MRC2, EGR1, and OTUD1) were considered cardiac hypertrophy and HF regulators." (PMID 37498303, 2023). "Six hub genes (TANC2, ADAMTS2, DYNLL1, MRC2, EGR1, and OTUD1) showed anomaly trend in cardiac hypertrophy." (PMID 37498303, 2023).
Ehlers-Danlos syndrome (10 papers, 2016 to 2026). The Ehlers–Danlos syndromes (EDS) are a clinically and genetically heterogeneous group of heritable connective tissue disorders (HCTDs) characterized by joint hypermobility, skin hyperextensibility, and tissue fragility. "Inactivation of ADAMTS2 has been associated with Ehlers-Danlos syndrome, a disorder affecting collagen formation and function." (PMID 38198533, 2024). "The second variant is a homozygous deletion in ADAMTS2, a gene that encodes a procollagen proteinase associated with recessive Ehlers-Danlos syndrome (EDS), dermatosparaxis type." (PMID 37234784, 2023). "ADAMTS2 encodes a peptidase (collagen synthase) and extracellular excreted protein that has been reported to be responsible for Ehlers-Danlos syndrome (recessive heredity) and accelerate liver fibrosis; however, its expression is low in the brain." (PMID 27723809, 2016). "Additionally, homozygous mutations in ADAMTS2 cause Ehlers-Danlos syndrome (VIIC), features of which can include multiple tooth agenesis and dentin defects." (PMID 31533690, 2019). "Despite a thorough workup for bleeding diatheses, the etiology remained elusive until whole-genome sequencing revealed a homozygous mutation in the ADAMTS2 gene, confirming Ehlers-Danlos syndrome (EDS), dermatosparaxis type (dEDS)." (PMID 42261541, 2026). "Among the procollagen N-propeptidases (ADAMTS2, 3, and 14), ADAMTS2 is well-characterized through its involvement in a rare human disorder, Ehlers-Danlos syndrome (EDS) type VIIC." (PMID 35053160, 2021). "For now, since we do not observe deleterious variants in ADAMTS2 and are not aware of additional symptoms indicating Ehler-Danlos syndrome in these animals, we do not consider this disorder to likely be the cause of the reduced growth." (PMID 38198533, 2024).
gastric cancer (6 papers, 2020 to 2023). A primary or metastatic malignant neoplasm involving the stomach. "In gastric cancer, overexpression of ADAMTS2 is associated with poor clinical prognosis." (PMID 32102222, 2020). "Recent reports suggest that ADAMTS2 is overexpressed by gastric cancer cells, COL14A1 is downregulated in breast cancer cells, and ADAMTS15 functions as a tumor suppressor role in prostate cancer." (PMID 37552338, 2023). "A later study in gastric cancer also showed that the upregulated ADAMTS2 expression was relevant to poor prognosis." (PMID 35755807, 2022). "ADAMTS-2 was found to be overexpressed in gastric cancer fibroblast cells." (PMID 35053843, 2022).
Stroke (6 papers, 2018 to 2024). Sudden impairment of blood flow to a part of the brain due to occlusion or rupture of an artery to the brain. "Recently, we have reported results of a family-based genome wide association study (GWAS) for pediatric stroke pointing our attention to ADAMTS2 and ADAMTS12." (PMID 32817637, 2020). "Additionally, T294865 (ASHGV40042838) mapped within 350 kb of another gene ADAMTS2 associating with stroke at 5q35.3, while T297706 (ASHGV40043041) mapped to Sirtuin 5 (SIRT5) within 6 kb at 6p23." (PMID 35754821, 2022). "Therefore, biologically, it would be plausible that periodontitis through the interaction of TSH4 and ADAMTS2 and 12 is associated with stroke and cerebral aneurysms." (PMID 34065604, 2021). "Finally, the hypermethylation gene locus, ADAMTS2, has been associated with increased risk for vascular injury, stroke and aneurysm." (PMID 30341379, 2018).
cognitive decline (4 papers, 2022 to 2025). "Of note, a recent transcriptome study also identified ADAMTS2 as the gene most associated with cognitive decline in a cohort of patients suffering from Alzheimer's disease, and this ADAMTS2 expression was related to amyloid and tau accumulation." (PMID 40837410, 2025). "We have shown that tau pathology in the ACC and two genes (PRTN3 and ADAMTS2) are strongly associated with the rate of cognitive decline in the ROSMAP cohort." (PMID 35557837, 2022). "Tau load in the anterior cingulate and ADAMTS2, encoding a metallopeptidase, were the respective regional pathology and gene most associated with cognitive decline, while PRTN3, encoding a serine protease, was the key protective feature." (PMID 35557837, 2022). "Among the genes induced in excitatory neurons of PWH were ADAMTS2, whose over-expression predicts cognitive decline in AD42 and GPC2 that is upregulated in AD43." (PMID 41282152, 2025). "ADAMTS2 was ranked between 3rd and 6th by the tree-based algorithms for episodic memory and global cognitive decline." (PMID 35557837, 2022). "Transcriptomic analysis suggested a role for several genes in cognitive decline with ADAMTS2 and PRTN3 featuring prominently, while tau pathology in the ACC was the most predictive neuropathological index from the ROSMAP neuropathology data." (PMID 35557837, 2022). "PRTN3 levels decreased, while ADAMTS2 increased with cognitive decline." (PMID 35557837, 2022). "ADAMTS2, but not PRTN3, was related to amyloid and tau load in the previous study while LTF was not related to cognitive decline here." (PMID 35557837, 2022).
heart failure (3 papers, 2023 to 2025). Inability of the heart to pump blood at an adequate rate to meet tissue metabolic requirements. "Their results suggest that ADAMTS2 plays a key role in modulating the expression of other heart failure-related genes (including natriuretic peptide A (Nppa) and natriuretic peptide B (Nppb)) in response to isoproterenol treatment." (PMID 40837410, 2025). "They observed high TGFβ activity in cardiac fibroblasts and endothelial cells during the progress of heart failure, but ADAMTS2 overexpression (transcriptionally up-regulated by MYC) could reverse this, seemingly through the PI3K/AKT and mitogen-activated protein kinase (MAPK) pathways." (PMID 40837410, 2025).
liver fibrosis (3 papers, 2016 to 2022). "ADAMTS2-deficient mice show reduced hepatic fibrosis in chronic liver injury induced by CCl4, whereas a single CCl4 injection causes a similar acute liver injury in knockout and wild-type mice." (PMID 27800489, 2016). "Studies showed that the collagen deposition rate of ADAMTS-2-deficient mice was slower than that of wild mice, that is, ADAMTS-2 reduced the degree and stability of liver fibrosis in mice, suggesting that ADAMTS-2 may promote liver fibrosis in mice." (PMID 35883515, 2022). "However, it is unclear whether ADAMTS2 level is elevated in patients with liver fibrosis and whether ADAMTS inhibitors ameliorate fibrosis progression and/or accelerate the regression in animal models." (PMID 27800489, 2016).
pancreatic cancers (3 papers, 2020 to 2023). "ADAMTS2 was also recognized as a crucial ECM-related regulator in pancreatic cancer." (PMID 37700248, 2023). "SPSB4 was identified among five genes, ADAMTS2, HOXA1, PCDH10, SEMA5A and SPSB4, that were highly/frequently methylated in liquid biopsies of pancreatic cancers although with a relatively low potential compared with the other four markers." (PMID 34062897, 2021). "Of the three criteria, we identified eight genes that were the most highly/frequently methylated in pancreatic cancers (PCDH10, SPSB4, HOXA1, ADAMTS2, BMP3, C13orf18, CCND2, and SEMA5A)." (PMID 32520974, 2020).
prostate carcinoma (3 papers, 2022 to 2026). A carcinoma that arises from epithelial cells of the prostate gland. "We identified ancestry-linked germline and somatic mutation frequencies in DNA damage repair genes (BRCA1, BRCA2, APC, and ATM), as well as three novel prostate cancer–associated genes (CACNA2D2, SYNE1, and ADAMTS2)." (PMID 36922933, 2022).
schizophrenia (3 papers, 2019 to 2025). A major psychotic disorder characterized by abnormalities in the perception or expression of reality. "A 2012 transcriptome study revealed a strong association between increased ADAMTS2 expression and schizophrenia in blood from affected individuals." (PMID 40837410, 2025). "This association was confirmed in two independent drug studies, where ADAMTS2 expression was reverted to “normal” levels in schizophrenia patients' peripheral blood mononuclear cells upon antipsychotic treatment targeting dopamine neurotransmission at the D1 and D2 receptors." (PMID 40837410, 2025). "Amplified ADAMTS2 activity may potentially lead to Reelin inactivation, which has also been suggested to play a role in schizophrenia." (PMID 40837410, 2025). "Using a new cohort of drug-naïve schizophrenia patients with clinical follow-up, we confirmed that the expression of ADAMTS2 was highly upregulated in PBMCs at the onset (drug-naïve patients) and downregulated, in clinical responders, after treatment with antipsychotics." (PMID 31740729, 2019). "Thus, D1 receptors signaling towards CREB activation might participate in the onset and clinical responses to therapy in schizophrenia patients by controlling ADAMTS2 expression and activity." (PMID 40837410, 2025). "Thus, D1 receptors signalling towards CREB activation might participate in the onset and clinical responses to therapy in schizophrenia patients, by controlling ADAMTS2 expression and activity." (PMID 31740729, 2019).
amyloid (2 papers, 2022 to 2025). "While higher PRTN3 may be protective, an interaction between immune genes, the amyloid-related LTF, and the tau-related ADAMTS2 could provide insights into how amyloid accelerates tau pathology." (PMID 35557837, 2022).
cerebral aneurysm (2 papers, 2021 to 2025). "In a subsequent study, an ADAMTS2 variant was identified as a risk factor for cerebral aneurysm." (PMID 40837410, 2025). "On the other hand, genetic variations of the ADAMTS family such as ADAMTS2 and 12 have shown to reduce the integrity of the endothelial lining, which together with inflammatory processes and defective vascular remodelling might play a key role in cerebral aneurysms pathogenesis." (PMID 34065604, 2021).
colorectal cancer (2 papers, 2019 to 2025). A primary or metastatic malignant neoplasm that affects the colon or rectum. "Expression of ADAMTS2 was significantly associated with distant metastasis and at borderline value with cause of colorectal cancer specific death." (PMID 30679934, 2019).
dementia (2 papers, 2022 to 2025). Loss of intellectual abilities interfering with an individual's social and occupational functions. "In 217 clinical and neuropathologically confirmed AD versus 290 no-dementia controls donors, we identify 613 differentially expressed genes (390 up, 223 down; |log2 fold change| ≥ 0.5; BH P < 0.05), with NPNT and ADAMTS2 among the top upregulated signals." (PMID 41278792, 2025).